RNU6-53P (RNA, U6 small nuclear 53, pseudogene)
Synonyms: RNU6-53
Gene: Small nuclear RNA gene on chromosome 13 (28,703,702 to 28,703,807, reverse strand). Ensembl gene ENSG00000202237.
Homologues: Orthologues: chimpanzee U6 (98% identical), macaque U6 (95% identical), dog U6 (82% identical), guinea pig U6 (77% identical), dog U6 (74% identical). Paralogues in human: RNU6-24P (88% identical), RNU6-378P (88% identical), RNU6-12P (87% identical), RNU6-13P (87% identical), RNU6-266P (87% identical), RNU6-26P (87% identical), RNU6-32P (87% identical), RNU6-338P (87% identical), RNU6-33P (87% identical), RNU6-49P (87% identical), RNU6-637P (87% identical), RNU6-698P (87% identical), and 1286 more.